ABCG2 (ATP binding cassette subfamily G member 2 (JR blood group))
Diseases named in the same sentence as ABCG2 in open-access papers (continued):
Sharing a sentence is not in itself a finding about the gene and the disease.
gout (continued). "Although the urate-raising GCKR and ABCG2 alleles were associated with both lower coffee consumption and higher risk of gout, mediation analysis demonstrated that these SNPs largely influence gout risk directly, rather than indirectly through their dual effect on coffee consumption." (PMID 29976226, 2018). "Thus, ABCG2 regulates UA levels via the extra-renal UA excretion, which is the major cause of extra-renal underexcretion, and gout." (PMID 29850377, 2018). "ABCG2 expression in the kidney proximal tubules and in the enterocytes has a key role in the systemic excretion of uric acid, and genome-wide association studies (GWAS) showed a significant link between gout and genetic variations in ABCG212–14." (PMID 29749379, 2018). "Similarly, in mediation analysis of ABCG2, a strong direct effect of the urate-associated SNP on gout risk was demonstrated (beta 0.848, SE 0.049, P < 1.00 × 10−8)." (PMID 29976226, 2018). "Mutations in ABCG2 are known to be associated with hyperuricemia and the risk of gout." (PMID 29558500, 2018). "In these models, the association of both GCKR and ABCG2 with gout were also observed." (PMID 29976226, 2018). "The urate-associated SNPs for both GCKR and ABCG2 were significantly associated with gout." (PMID 29976226, 2018). "ABCG2 is also involved in uric acid elimination and its impaired function is causative in gout." (PMID 29749379, 2018). "Furthermore, ABC transporter subfamily G member 2 (ABCG2) regulates mitochondrial respiration, and is associated with gout." (PMID 29976239, 2018). "In addition to rs2231142, haplotype analysis of polymorphisms in ABCG2 revealed SNP-derived haplotypes associated with gout risk." (PMID 28855613, 2017). "The ABCG2 risk alleles have been associated with allopurinol resistance, and it is possible that these variants lead to relative hyperuricaemia even with urate-lowering therapy, increasing the risk of tophaceous disease." (PMID 28270222, 2017). "Specifically, the functional Q141K variant of the urate transporter ABCG2, which is strongly associated with hyperuricemia and gout, and compellingly with early onset and tophaceous gout, may inhibit autophagy and modulate systemic inflammation." (PMID 28818081, 2017). "Our results, combined with those from previous studies, suggest that genetic variation in ABCG2 may influence gout susceptibility in the Han Chinese population." (PMID 28855613, 2017). "However, the observed significant decrease in the in vitro transport activity suggests that patients harboring these variant alleles are at risk for adverse effects of ABCG2 substrates or diseases linked to ABCG2 function, such as gout." (PMID 28281205, 2017). "We have previously reported that a non-synonymous SLC2A9 Arg265His variant is associated with tophi in New Zealand Māori with gout, and a Taiwanese study has reported an association between ABCG2 Q141K and tophi in both Han Chinese and Taiwanese aboriginal people with gout." (PMID 28270222, 2017). "The objective of the present study was to determine whether there was an association between single nucleotide polymorphisms (SNPs) in ABCG2 and gout." (PMID 28855613, 2017). "We found that 24 SNPs in ABCG2 are susceptibility loci associated with gout." (PMID 28855613, 2017). "In addition, we previously reported that ABCG2, which also locates in a gout-susceptibility locus on chromosome 4q21–31, is strongly associated with gout." (PMID 25326865, 2015). "Multiple evidences indicated that the common variants in ABCG2 could reduce the transport function and result in the hyperuricemia and gout." (PMID 24513273, 2014). "The recent findings on the roles of the ABCG2 Q141K and Q126X polymorphism in gout may pave the way for pharmacological chaperones targeting ABCG2 as a potential new therapeutic target for gout." (PMID 24857923, 2014).
gout (continued). "When analyzing gout as the phenotype, two loci reached genome-wide significance: a novel association with an exonic SNP in ALDH16A1 (P = 1.4 × 10−16), and a Q141K variant within ABCG2 (P = 2.82 × 10−12), a gene previously reported to be associated with gout and serum uric acid levels." (PMID 25789374, 2014). "The aim of this study was to test the hypothesis that the ABCG2 gout risk allele 141 K also promotes the serum urate response to fructose loading." (PMID 24476385, 2014). "In the present study, we developed an HRM assay to detect three functional SNPs (Q141K, V12M and Q126X) and then assessed the genetic association of those SNPs in the ABCG2 gene with gout to investigate the association between ABCG2 dysfunction and gout risk in a Han Chinese male population." (PMID 24857923, 2014). "Additionally, genotype combinations with full ABCG2 function were detected in 46.6% of the normal subjects but in only 21.6% of the gout patients with other risk factors for gout." (PMID 24857923, 2014). "Furthermore, pharmacochaperones have been suggested as a treatment option in gout cases caused by incomplete folding and decreased functional activity of the ABCG2 variant Q141K." (PMID 24316454, 2014). "As ABCG2 and SLC2A9 are the two major genetic risk factors for gout, we wished to examine whether variation in ABCG2 also contributes to serum urate responses to a fructose load." (PMID 24476385, 2014). "This study aimed to test the hypothesis that the ABCG2 gout risk allele 141 K promotes the hyperuricaemic response to fructose loading." (PMID 24476385, 2014). "Moreover, the risk of gout is markedly increased by severe ABCG2 dysfunction, conferring an adjusted OR of 5.90." (PMID 24857923, 2014). "SNP markers in SLC2A9 and ABCG2 genes were found to be strongly associated with the phenotype gout." (PMID 19890391, 2009). "In addition to the Q126X and Q141K variants evaluated in the present study, there might be other genetic factors that affect hyperuricemia/gout with large effect sizes, such as rare variants of ABCG2 and variants of other genes." (PMID 41452549, 2025). "Genome-personalized nursing for gout/hyperuricemia could therefore be promoted by recommendations to reduce body weight and alcohol intake to match individuals’ genetic variations, i.e., ABCG2 variants." (PMID 41452549, 2025). "Moreover, ABCG2 dysfunction was reported as a strong independent risk for paediatric-onset hyperuricemia/gout and the role of the ABCG2-Q141K mutation has been shown in younger hyperuricemic/gout individuals." (PMID 35939175, 2023). "Therefore, the increase in the expression of this cytokine could be a biomarker of damage and inflammation in patients with gout and its increase together with ABCG2 in the blood could be associated with a presymptomatic state." (PMID 35505381, 2022). "Although the mechanisms of action for the inadequate response are still unclear, other SUA-lowering drugs may be somewhat better in terms of efficacy for patients with a dysfunctional ABCG2 allele, which puts them at higher risk of developing hyperuricemia/gout." (PMID 33669292, 2021). "Non-synonymous allelic variants, common and rare, of ABCG2, had a significant effect on the earlier onset of gout and the presence of a familial gout history, and ABCG2 dysfunction was reported as a strong independent risk for paediatric-onset hyperuricemia/gout." (PMID 34946365, 2021). "In addition, ABCG2 rs2231142 considered a risk allele for gout." (PMID 34335246, 2021). "However, compared with adult-onset gout, little clinical information is available regarding the association of other uricemia-associated genetic variations with early-onset gout; the latent involvement of ABCG2 in the development of this disease requires further evidence." (PMID 33669292, 2021). "In addition, ABCG2 is also associated with the prevalence and onset of gout." (PMID 32180207, 2020).
gout (continued). "Such variants include the widely prevalent ABCG2 Q141K (rs2231142), which has a particularly high allele frequency (up to ~30%) in multiple East Asian populations at large and, not unexpectedly, an even higher allele frequency (up to ~50%) in gout patients from those populations." (PMID 33330529, 2020). "In addition, allopurinol (or its metabolites), applied for reducing hyperuricemia and treating gout, is also a substrate of ABCG2, thus, patients carrying a reduced function ABCG2 variant may have reduced response to allopurinol." (PMID 31597297, 2019). "The ABCG2 protein is involved in endobiotic and xenobiotic transport, thus processing and trafficking mutants of this protein may increase the susceptibility to gout and also increase drug toxicity." (PMID 31597297, 2019). "Thus, ABCG2 dysfunction is also a major cause of gout in Han Chinese individuals." (PMID 24857923, 2014). "Since ABCG2, expressed on the apical side of the proximal tubular cells in human kidney, plays a pivotal role in renal excretion of serum uric acid, long-term inhibition of renal ABCG2 can cause gout and/or enhance the risk of cardiovascular disease and diabetes." (PMID 24310600, 2011). "NRBP1 inhibition plays an important role in alleviating hyperuricemia and gout by upregulating ABCG2 through the Wnt/β-catenin signaling pathway in HK-2 cells." (PMID 41311848, 2025). "Since hyperuricemia is the key known factor that leads to gout, many of the consistently top-associated genes, such as SLC2A9, SLC22A12, or ABCG2, are involved in urate transport." (PMID 41155224, 2025). "The top gene ABCG2 (p = 8.26 × 10−9, FDR = 1.51 × 10−4) was associated with olanzapine-induced LDL changes; this gene is related to gout, urate measurement, and BMI based on information from the Open Target Platform." (PMID 40830362, 2025). "Genetic studies have identified urate transporter variants in genes such as ABCG2 and SLC2A9 as major determinants of serum urate levels and gout risk, with several risk alleles reported to be more prevalent in East Asian populations." (PMID 41465815, 2025). "Based on these insights, we focused on investigating ABCG2, a urate acid transporter whose dysfunction is linked to HUA and gout, as a potential target of ISL during the injury repairment." (PMID 40303869, 2025). "The complicated relationship between the genes URAT1, GLUT9, ABCG2, HPRT1, XOR, and uricase shows the complex genetic framework that controls the metabolism of uric acid and the risk of gout." (PMID 39598418, 2024). "This single SNP also expressed the greatest effect on gout and hyperuricemia among other SNPs on the ABCG2 gene." (PMID 39315221, 2024). "In gout patients, iron overload activates xanthine oxidase and inhibits the expression of ATP-binding cassette subfamily G, member 2 (ABCG2), leading to increased uric acid production and decreased excretion." (PMID 39606034, 2024). "ABCG2 is expressed in various tissues, including the kidney and intestine, and its dysfunction leads to hyperuricemia and gout." (PMID 39088565, 2024). "Overall, the SLC family, particularly SLC22A12 and SLC2A9 along with ABCG2, play important roles in UA transportation, and their dysfunction can contribute to hyperuricemia and gout." (PMID 38674582, 2024). "Febuxostat is widely used in clinical practice to lower level of uric acid in patients with gout; its clinical effect has been attributed to its ability to interfere with the urate transport function of ABCG2." (PMID 38442133, 2024). "Within the gene loci associated with the risk of gout identified, SLC2A9 and ABCG2 have the strongest effect on serum urate concentration in the context of complex phenotype loci." (PMID 39433541, 2024). "At least 10% of all gout cases in persons of European ancestry are attributable to a loss of function variant of ABCG2Q141K, which influence ABCG2 expression in a tissue-specific manner and is responsible for extra-renal uric acid under-excretion." (PMID 39433541, 2024).
gout (continued). "ABCG2, a urate exporter, is expressed in various tissues including the kidney and intestine, and its dysfunction leads to hyperuricemia and gout." (PMID 36639673, 2023). "The ATP-binding cassette (ABC) transporter ABCG2 is a significant urate transporter with a high capacity, and it plays a crucial role in the development of hyperuricemia and gout." (PMID 38067624, 2023). "Gouty patients with functional ABCG2 SNPs have developed gout significantly earlier, with an estimated average (SE) of 8.1 (3.0) years in their life compared to gouty patients who did not have ABCG2 mutation/variants (p = 0.008)." (PMID 35939175, 2023). "This study confirmed that pairs of rs2728121 in PKD2 and rs1481012 in ABCG2 can impact the etiology of elevated serum urate, hyperuricemia, and gout, which supports the fact that rs1481012 discovered in this study influences gout." (PMID 38060535, 2023). "The ABCG2 gene contributes to inflammation in gouty arthritis that is mediated via the release of Interleukin 8 (IL-8) following MSU crystals-stimulation in an endothelial cell model." (PMID 36967798, 2023). "Effects of the interaction between PKD2 and ABCG2 on gout has been studied in Chinese and Japanese male populations, respectively." (PMID 38060535, 2023). "We identified 15 SNPs related to gout, among which rs1481012 of ABCG2 located on chromosome 4 has been newly discovered (P = 2.46e-11)." (PMID 38060535, 2023). "Understanding the role of ABCG2 in different organs of patients with gout will allow knowing the key points of its dysregulation." (PMID 35505381, 2022). "The cytokine IL-1β participation in the response to MSUs in gout attack has long been known, but little is known about its effect on ABCG2 and its interaction with other urate transporters." (PMID 35505381, 2022). "An ABCG2 SNP (rs2231142) enhances this autophagic impairment, diminishes the formation of neutrophil extracellular traps, and aggravates gout via the overactive release of the NLRP3 inflammasome and IL-1β." (PMID 35813212, 2022). "The alpha kinase 1 variant in combination with the ABCG2 SNP (rs2231142), the SLC2A9 SNP (rs1014290), or the SLC22A12 SNP (rs475688 and rs3825016) is linked to gout in the recessive model." (PMID 35813212, 2022). "Two major LD blocks relating to gout were observed in chromosome 4 which is located on the p arm and q arm; the major causal genes are SLC2A9 and ABCG2, respectively." (PMID 36221101, 2022). "Human genomic studies have identified many urate transporter genes, including ABCG2, SLC22A12, SLC2A9, and OAT4 as risk factors for gout by conducting genome-wide analyses and meta-analyses." (PMID 36139553, 2022). "The results showed ABCG2 gene was involved in four phenotypes, except for those developing hyperuricemia and gout (compared to AH) under the selection of rs2231142 wild type." (PMID 36221101, 2022). "In white, African and Asian populations, the SNP rs2231142 in exon 5 of the ABCG2 gene, which generally causes the Gln141Lys amino acid substitution, is the strongest link between ABCG2 and gout/hyperuricemia." (PMID 36483739, 2022). "A genomic study analyzed the epistasis of ALPK1 with the loci of GLUT9, ALPK1, SLC22A12, and ABCG2, finding a positive predictive value (PPV ≥ 81%) to measure the risk of gout (OR ≥ 12.30) using variants of these genes in different populations." (PMID 35505381, 2022). "Two additional SNP variants (rs2231142.GG of ABCG2 and rs11231463.GG of SLC22A9/OAT7) were selected based on their contributions to gout in the development cohort and their reported effects on renal urate handling." (PMID 35264217, 2022). "Considering ABCG2 genotypes will be beneficial for patients with early-onset and/or familial hyperuricemia and gout." (PMID 33669292, 2021). "In the context of hyperuricemia/gout, there are about 50 allelic variants, including a number of rare variants with minor allele frequencies (MAF) < 0.01%, which have been found in the ABCG2 gene." (PMID 33669292, 2021).
gout (continued). "Moreover, another ABCG2 SNP rs1448784 was located within the 3′-untranslated region and found to confer great susceptibility to gout; this could be taken into consideration in future studies, in addition to the two most commonly studied missense SNPs, rs2231137 and rs2231142." (PMID 34680995, 2021). "Taken together, ABCG2 is known to be a key genetic determinant regarding the onset of gout; additionally, it plays a role in the progression and severity of the disease, and is associated with a poor response to allopurinol." (PMID 34946365, 2021). "Our findings illustrate why genetic factors affecting ABCG2 function should be routinely considered in clinical practice as part of a hyperuricemia/gout diagnosis, especially in pediatric-onset patients with a strong family history." (PMID 33669292, 2021). "ABCG2 encodes a high-capacity transporter for urate efflux and the ABCG2 rs2231142 single nucleotide polymorphism (SNP) is one of the most prominent genetic variants associated with HUA and gout." (PMID 34531894, 2021). "In that previous study, a group of healthy volunteers and patients with clinically verified gout or hyperuricemia was screened for low ABCG2 expression levels." (PMID 33634118, 2021). "Selection pressure analysis revealed significant enrichment of selection pressure on ABCG2 in addition to ALDH2 loci for all subtypes except for normal type gout." (PMID 32238385, 2020). "Many more individual studies have replicated the findings of GWASs and these were summarized in systematic reviews of the effects of ABCG2 and SLC2A9 polymorphisms on gout." (PMID 33087043, 2020). "Our results uncover that epistatic interactions between PKD2 and ABCG2 influence all progressions from elevated serum urate to gout." (PMID 32000861, 2020). "Because genetic variants in urate transporter genes such as ABCG2, SLC2A9 and SLC22A12 are well known to cause SUA variation and gout, it is also possible that the SLC38A1/SNAT1 transporter is involved in urate or purine transport." (PMID 32238385, 2020). "Observational studies in adults with any polymorphism in ABCG2 or SLC2A9, and outcome including gout, hyperuricemia, and serum urate were included for pooling." (PMID 33087043, 2020). "Considering the effect of ABCG2 SNPs on gout, effects of rs2231142 were consistent with the recent updated meta-analyses that pooled allele and genotype effects." (PMID 33087043, 2020). "We provide genetic epidemiological evidence supporting a role for ABCG2 141K in the progression from HU to gout, additional to its role in promoting HU." (PMID 32164793, 2020). "Genome-wide association studies (GWAS) have shown that many single nucleotide polymorphisms (SNPs) of ATP-binding cassette sub-family G member 2 gene (ABCG2) and the solute carrier family 2 member 9 (SLC2A9) are associated with serum urate and gout." (PMID 33087043, 2020). "We conducted a systematic review and meta-analysis to assess associations between SNPs in ABCG2 and SLC2A9 and gout, hyperuricemia and serum urate, stratified by ethnicity." (PMID 33087043, 2020). "Recent GWASs of clinically defined gout have revealed associations between gout and urate transporter genes, such as ABCG2/BCRP, URAT1/SLC22A12, GLUT9/SLC2A9, NPT1/SLC17A1, all of which are expressed in the proximal tubular cells of the kidney." (PMID 31975031, 2020). "Our study explored the effect of epistatic interactions between PKD2 and ABCG2 on the progression from elevated serum urate to gout." (PMID 32000861, 2020). "Transporters URAT1 and NPT1 (present at proximal renal tubule) and also GLUT9 and ABCG2 (present at both proximal renal tubule and enterocytes) are the key regulators of serum urate (SU) levels in patients with hyperuricemia and gout." (PMID 33117824, 2020).